PDGFB (platelet derived growth factor subunit B)
Diseases named in the same sentence as PDGFB in open-access papers (continued):
Sharing a sentence is not in itself a finding about the gene and the disease.
tumor (continued). "However, PDGFB-to-PDGFR-β tumor–stroma signaling also promotes the initiation and metastasis of cancer cells in the context of BC." (PMID 40248695, 2025). "Tumor-associated myeloid cells and microglia (TAMs) (key components of the GBM microenvironment) contribute to GBM progression by secreting cytokines and chemokines, such as PDGFB, EGF, SDF-1α, IL-6, and IL-8." (PMID 40867240, 2025). "Second, we combined Ppm1d with the relatively strong oncogene platelet-derived growth factor B (PDGFB) to increase tumor penetrance, but PDGF receptor alpha (PDGFRA) may be a more faithful alteration found in human DMG10." (PMID 41394550, 2025). "Consistent with the in vitro results, PDGFB knockout in CAFs could dramatically reduce their promotion of tumor growth in vivo." (PMID 37307823, 2024). "Other ligand-receptor pairs revealed by this analysis included TNF-TNFRSF1A sent by medium-SORL1 expressing GAMs, TNFSF12-TNFRSF12A (high-SORL1 GAMs to tumor cells), PDGFB-PDGFRA (medium- and high-SORL1 GAMs to several populations), and THY1-(ITGAM + ITGB2) received by high-SORL1 GAMs (Fig. EV2B)." (PMID 38499808, 2024). "Furthermore, we observed high levels of factors associated with tumor cell proliferation (CDCP1, EpCAM, EGFR, and PDGFB)." (PMID 38942797, 2024). "Tumor-secreted PDGFB stimulates tumor LYM and further promotes lymph node metastasis, and PDGFB may be an effective target for inhibiting LYM, which could explain the association between PDGFB and the LYM index." (PMID 38638428, 2024). "PDGFB as a platelet activation factor for promoting tumor metastasis by recruitment of TAMs." (PMID 37065499, 2023). "In addition, primary PDGFB-driven tumor cells increase CCL2 expression in response to recombinant IL-1β (rIL-1β)." (PMID 37733448, 2023). "Thus, MDSC accumulation in tumours promoted tumour growth, while PDGFB overexpression restored PC coverage and abolished the increased MDSC trafficking to PC-deficient tumours." (PMID 36831136, 2023). "Since PDGFB-driven tumor is mainly monocyte-enriched, we next wanted to determine whether compensatory recruitment of neutrophils is a GBM-specific or CNS-specific phenomenon." (PMID 37012245, 2023). "To determine whether loss of MCPs in tumor cells drives mesenchymal transition, we generated primary GSC cultures of PDGFB-driven GBM generated in qMCP−/−; Ntv-a mice (“qMCP−/−-GSCs”) and compared MES signature gene expression to WT-GSCs by qPCR." (PMID 37012245, 2023). "Unsupervised clustering identified 5 major cell classes in these tumors, as observed for PDGFB tumors: lymphoid and myeloid immune cells, stromal cells, endothelial cells, and malignant tumor cells, with myeloid cells accounting for most of the nonmalignant cells." (PMID 37733448, 2023). "Pharmacological targeting of neutrophils and their chemokine receptor CXCR2, or genetic ablation of the neutrophil recruiting chemokine Cxcl1, results in extended survival of PDGFB-driven tumor-bearing qMCP-deficient mice but not WT tumor-bearing mice." (PMID 37012245, 2023). "In addition, the conjugation of PDGFB cycle peptides makes the nanoswitch recognize the tumor site specifically, allowing the nanoswitch to be effectively internalized by tumor cells and accumulate preferentially at tumor sites." (PMID 36609374, 2023). "For instance, PDGFB expression has been closely linked to the development of tumor stroma in melanoma, and PDGFA facilitated recruitment of PDGFR-positive stromal fibroblasts to tumor periphery in xenograft mouse models of lung carcinoma." (PMID 38234683, 2023). "Interestingly, PDGFRB/PDGFB are in closer proximity to disease genes in the Basal-like subnetwork further supporting evidence for its role in tumor aggressiveness." (PMID 37200395, 2023).
tumor (continued). "The tumor-specific nanoswitch is designed and manufactured on the basis of PDGFB-conjugating ferroferric oxide coated by Mn-doped silica (PDGFB-FMS), which can be degraded under the high-concentration GSH and low pH in TME to activate the T1–T2 dual-mode MRI signals." (PMID 36609374, 2023). "Of special interest, PDGFB (platelet-derived growth factor) plays a pivotal role in tumor angiogenesis and growth, facilitated by the consistent activation of platelets in the tumor microenvironment (TME), driven by comparable activation signals found in wound healing processes." (PMID 37958805, 2023). "The amount of tumor-associated PDGFB protein showed a 10-fold reduction in mice lacking PDGFB in platelets." (PMID 35454853, 2022). "Overexpression of PDGFB promotes recruitment of pericytes, which may serve as gatekeepers against tumor invasion and metastasis." (PMID 35378770, 2022). "There are previous publications describing the role of PDGFB/PDGFRs in tumor ECM remodeling." (PMID 35454853, 2022). "Of note, many cytokines which activate the tumour microenvironment, including platelet-derived growth factor, B polypeptide (PDGFB), interleukin-6 (IL6), chemokine (C–C motif) ligand 2 (CCL2), and leukaemia inhibitory factor (LIF) were included as targets of TGF-β." (PMID 33674758, 2021). "PDGFB stimulation initiates tumor formation by stimulation of neural/glial progenitor cells." (PMID 27806344, 2016). "Macrophages isolated from HCC tumor tissue expressed significantly higher levels of VEGFA and PDGFB mRNA compared to those detected in non-tumor-infiltrating macrophages (approximate 2.07-fold upregulated, P = 0.015 and approximate 2.33-fold upregulated, P = 0.011, respectively, n = 7)." (PMID 24194900, 2013). "To elucidate how the presence of PDGFB in the nucleus impacts the chromatin landscape, we performed single cell RNA sequencing (scRNA-seq) and single cell transposase-accessible chromatin with sequencing (scATAC-seq) on PDGFBΔNLS, PDGFBwt and non-tumor mouse brains." (PMID 40060572, 2025). "Therefore, cells with high expression of KK-LC-1 may inhibit the MAPK signaling pathway by downregulating TGFA and PDGFB, thus showing enhanced anti-tumor immune response." (PMID 38972967, 2024). "First, we demonstrate that genetic loss of individual MCP genes in stromal cells results in improved survival of PDGFB-driven tumor-bearing mice with no change in myeloid content, while loss of individual MCPs from both stromal and tumor cells abolishes survival advantage." (PMID 37012245, 2023). "However, when the tumor is targeted, the weakly acidic and high GSH of TME disrupts the PDGFB-FMS, causing its nanostructure to collapse, resulting in the rapid release of Mn2+ ions, which separates from the Fe3O4 magnetic core and activates the dual-mode of the T1 and T2 MRI signals." (PMID 36609374, 2023). "Activation of PPARβ in blood vessels promotes tumor vascularization and the progression of different cancer cell types through direct activation of platelet-derived growth factor receptor beta (PDGFRβ), platelet-derived growth factor subunit B (PDGFB), and the c-Kit." (PMID 32028670, 2020). "The COL1A1-PDGFB fusion gene was detected in both imatinib-resistant and imatinib-sensitive tumors and COL1A1-PDGFB rearrangement was reconfirmed by PCR, but no point mutation or copy number change was detected in the PDGFB gene of the imatinib-resistant tumor." (PMID 23922791, 2013). "Biodistribution and proteomic analyses confirmed efficient BBB penetration, tumor-selective accumulation, and suppression of VEGFA/C, MMP-9, PDGFB, and SERPINE1." (PMID 41993637, 2026). "Its activation, driven by tumor-infiltrating microglia and macrophage-derived extracellular factors such as EGF, PDGFB, SDF-1α, IL-6, and IL-8, enhances tumor cell motility and survival." (PMID 40867240, 2025).
tumor (continued). "Endothelium, an abundant source of platelet-derived growth factor B (PDGFB), is capable of recruiting PCs into the blood vessel by binding to PDGFR-β to sustain the integrity and stability of tumor blood vessels." (PMID 40248695, 2025). "PPARD agonists promote the expression of platelet-derived growth factor receptor beta, platelet-derived growth factor subunit B, and the tyrosinkinase KIT to promte tumor angiogenesis and progression." (PMID 38212774, 2024). "Survival was only improved in PDGFB-driven GBM models, suggesting that tumor cell genotype influenced the immune TME." (PMID 37966120, 2023). "PDGFB-FMS has been utilized for the precise diagnosis of heterotopic and orthotopic tumors due to its increased SNR and tumor-specificity." (PMID 36609374, 2023). "In concert, tumor cells and CAFs secrete pro-angiogenic factors such as VEGF, FGF2, PDGFA and PDGFB." (PMID 37091337, 2023). "Platelet derived growth factor subunit B (PDGFB) was identified as a target of miR-363-5p, suggesting a potential mechanism for the tumour suppressive effect." (PMID 37670020, 2023). "MCP levels were elevated in PDGFB-driven GBM compared with normal brain, and treatment of these tumor cells with IL-1β increased MCP expression concomitant with increased NF-κB activation via phosphorylation." (PMID 37966120, 2023). "It results in fusion of the promoter of the collagen type Iα1 gene (COL1A1) and the platelet-derived growth factor B-chain (PDGFB) genes, which ultimately contribute to continuous autocrine production of local PDGF, promoting tumour growth." (PMID 35406465, 2022). "The results showed that the growth factor LR interacts with PDGFB : PDGFRA, IGFBP4:FZD8, and TGFB1:SDC2 with TAMs and tumor vascular cells." (PMID 35664733, 2022). "In the current study, we present for the first time, in vivo evidence for a connection between platelet-derived PDGFB and ECM deposition in the tumor microenvironment." (PMID 35454853, 2022). "Immunohistochemical results showed that the expression levels of CD31, PDGFB, VEGF, VWF, and PDGFRB in the HCC-PDX tumor tissues were all downregulated by MTE in a dose-dependent manner." (PMID 35847002, 2022). "Many immune cells which infiltrated into the tumor microenvironment secrete a variety of cytokines including TGF-β, SDF-1, PDGFB to promote the migration and transformation of cancer stem cells." (PMID 33946480, 2021). "The result of this rearrangement is the upregulation of COL1A1-PDGFB fusion proteins that are processed to form mature PDGFB and then to activate PDGFRB to form an autocrine loop, rendering tumor cell proliferation and survival dependent on PDGFRB signaling." (PMID 34362454, 2021). "To further select the key genes in the complex network, we analyzed all of genes integrating with the clinical categories and found that TGFβ2, GNG11, PDGFB, and ITGA5 were changed among different patients’ tumor stages, states, T categories, and grades." (PMID 33115518, 2020). "Herein, stromal cell production of PDGFB (presumably by ECs) is crucial as transgenic expression of PDGFB by T241 fibrosarcoma cancer cells could only rescue pericyte recruitment to the tumor in mice bearing a mutated Pdgfb gene, but not proper localization to tumor vessels." (PMID 30949450, 2019). "Once PDGFB is cleaved from the COL1A1-PDGFB chimeric protein, it stimulates tumor cells to go into an autocrine fashion, thus, leading to proliferation transformation." (PMID 31692830, 2019). "Tumour Thrombospondin-1 (THBS1), Annexin II (ANXA2) and PDGFB were found to have the highest connectivity with genes of the stromal compartment." (PMID 30850588, 2019). "Mounting research has shown that many tumours secrete a diversity of angiogenic factors (such as VEGFA, PDGFB, bFGF and EGF) to promote tumour angiogenesis." (PMID 30584257, 2018). "To provide evidence that IDH1R132H is tumor-suppressive, we engineered a RCAS vector that expresses IDH1R132H, P2A, and PDGFB from the same transcript." (PMID 30416682, 2018).
tumor (continued). "Accumulating data indicate that tumour cells secrete several angiogenic factors (VEGF, PDGFB, and bFGF) to promote angiogenesis." (PMID 30060750, 2018). "Importantly, western blot analyses showed that along with these augmented levels of lytic gene expression, PDGFA and PDGFB correlated with prominent PDGFRA phosphorylation in tumor samples, suggesting that it could be a result of lytic induction occurring during in vivo tumorigenesis." (PMID 29985958, 2018). "Taken together, these results support the selection against IDH1R132H transgene in PDGFB-driven tumors and the dependence of IDH1R132H expression on inactivation of tumor-suppressor gene(s)." (PMID 30416682, 2018). "A diversity of angiogenic factors (such as VEGFA, PDGFB, bFGF and EGF) secreted from tumour cells have been reported to play an important role in tumour angiogenesis." (PMID 30584257, 2018). "Further, the combination of PDGFB and BIRC3 resulted in a significant decrease in tumor-free survival compared to controls." (PMID 27074575, 2017). "Accordingly, we demonstrate that while PPARG agonism accelerates AML growth, PPARG antagonism is inhibitory, strongly suppressing AML proliferation and tumor‐initiating capacity, via a TGFB‐mediated inhibition of PDGFB and CTGF." (PMID 28275008, 2017). "PDGFB and PDGFRB are less expressed relatively to PDGFC in perinecrotic zone, and also in comparison to PDGFRA in cellular tumour block." (PMID 29127351, 2017). "Our results showed that each inhibitor had the effect on the proliferation and apoptosis of the PDGFB/H3K27M NSCs, interestingly, combination of these two inhibitors exhibited better effect on suppressing growth of the tumor cells." (PMID 29118968, 2017). "We then examined the influence of LY6E on tumor vasculature because we confirmed that LY6E significantly induced the expression of pro-angiogenic factors, such as VEGF and PDGFB." (PMID 27589564, 2016). "We did not detect any tumors in co-injected mice that had lost either the PDGFB cDNA or the PTN cDNA construct, indicating that the combined expression of both genes enhanced tumor formation." (PMID 27806344, 2016). "One tumor had both Ink4a/ARF region deletion and EGFR amplification, however total and phosphorylated EGFR levels in this tumor were low and PDGFB was present." (PMID 19915670, 2009). "Interestingly, we found that ESM1 and PDGFB are expressed in the same tumor regions, while PDGFA and PDGFC seem to be mutually exclusive with PDGFB and ESM1." (PMID 39773984, 2025). "Our results indicated that HSV-PDGFi-shRNA could significantly downregulate the PDGFB level in the xenografts, but PDGFA level, and PDGFBB knockdown effectively inhibited tumor growth." (PMID 38378786, 2024). "We also confirmed that 4 genes (PECAM1, TIMP1, CXCL5 and PDGFB) were correlated with the expression of the VEGF family, suggesting that these genes may work together with the VEGF family to promote tumor LYM." (PMID 38638428, 2024). "Strategies aimed at modulating the PDGFB signaling pathway and targeting EPH receptors could offer potential therapeutic avenues for controlling tumor cell survival, proliferation, and metastasis." (PMID 38233802, 2024). "Considering the paired sample differential analysis, expression correlation analysis, immunological and tumour microenvironment correlation analysis, as well as the line chart results, CEMACAM3, LCK, PARP1, PDGFB, PLK1, SEMA7A and SPHK1, were considered as prognostic genes of higher value." (PMID 39656479, 2024). "Abolishing monocytes had no impact on survival of neutrophil-enriched HCC tumor-bearing mice, similar to what we had shown with abolishing neutrophils in monocyte-enriched PDGFB-driven GBM." (PMID 37012245, 2023). "Here, we show that PDGFB-driven GBM cells induce the expression of the potent proinflammatory cytokine IL-1β in MDM, which engages IL-1R1 in tumor cells, activates the NF-κB pathway, and subsequently leads to induction of monocyte chemoattractant proteins (MCPs)." (PMID 37733448, 2023).
tumor (continued). "In two animal models, the lack of PDGFB in platelets resulted in increased hypoxia and epithelial-mesenchymal transition in initial tumors, elevated levels of circulating tumor cells, and increased spontaneous metastasis to the liver or lungs." (PMID 38020758, 2023). "Using these murine PDGFB-driven (PDGFB mGBM) and Nf1-silenced (Nf1 mGBM) GBM models that show differential myeloid recruitment, we investigated how IL-1α and IL-1β individually contribute to tumor development in vitro and in vivo." (PMID 37733448, 2023). "Single-Cell RNA-Seq reveals that the TAMs of PDGFB-driven proneural tumors is dominated by microglia and PLX3397 treatment can remodels the TAMs in this type of tumor by downregulating pro-tumor gene expression, leading to a favorable response to PLX3397 therapy." (PMID 37598273, 2023). "Moreover, OV cell-derived PDGFB was the primary source that activated PDGFRB in CAFs, indicating tumor cells promoted CAF formation." (PMID 37658364, 2023). "FISH utilizing the PDGFB break-apart probe revealed unbalanced translocation presenting additional 3’-red signals in 5% of these tumor cells, while the COL1A1-PDGFB fusion probe showed yellow signal denoting a fusion pattern in 2% of tumor cells." (PMID 36776313, 2023). "Thus, the data suggest a feed-forward loop in which PDGFB-driven GBM cells express MCPs that drive BMDM infiltration and IL-1β expression, further promoting tumor growth." (PMID 37966120, 2023). "scRNA-Seq of PDGFB and Nf1 mGBM revealed that Nf1 mGBM cells are more prominent contributors to the total pool of MCP transcripts compared with PDGFB tumor cells, further supporting the observation that Nf1-silenced mGBM cells express high levels of MCPs to recruit monocytes." (PMID 37733448, 2023). "BMDM cocultured with tumor cells induced both IL-1β expression and secretion; however, this effect was only observed using PDGFB mGBM tumors, but not Nf1-silenced mGBM cells." (PMID 37733448, 2023). "In GBM, TGFβ is an oncogenic factor, being able to induce proliferation in GSCs, indirectly by inducing the action of PDGFB, to determine self‐renewal, by further upregulating a second cytokine, LIF, and by also promoting tumour cell migration, among other functions." (PMID 35203105, 2022). "In addition, we also analyzed tumor angiogenesis genes, and the results showed that seven tumor angiogenesis genes (HIF1A, PDGFB, NRP1, VEGFB, FGFR1, ROBO1, and SLIT1) had substantially higher expression in the high-risk group compared with the low-risk group." (PMID 35311113, 2022). "Concerning HCC, it has been confirmed that the platelet-derived growth factors (PDGF, including PDGFA, PDGFB, PDGFC, and PDGFD) participate in modulating the tumor development and chemoresistance by interacting with its receptor PDGFR and activating the downstream signaling pathway." (PMID 36463115, 2022). "This indicates that PDGFB is not expressed by the actual tumor cells in this model and that ECs are the major source of PDGFB transcription in the TME." (PMID 35454853, 2022). "Also, the angiogenesis-related molecules including PDGFB, VEGF, VEGFA, and PDGFRB were significantly downregulated by MTE, especially by high-dose MTE in the HCC-PDX tumor." (PMID 35847002, 2022). "In PDAC tumor-bearing xenografted mice, injection of LIN28B-positive sEVs activated LIN28B/let-7/high-mobility group AT-hook 2 (HMGA2)/platelet derived growth factor subunit B (PDGFB) signaling to facilitate PDAC liver metastasis." (PMID 34638330, 2021). "For example, four growth factors (TGFB1, HGF, BMP1 and PDGFB) that are well-known to induce EMT, exhibited higher expression levels in CD4/8+ T cells compared with other immune and tumor cells, suggesting that anti-immune evasion promotes EMT as well by producing growth factors which induce EMT." (PMID 34158591, 2021).